NLRP3 (NLR family pyrin domain containing 3)
Diseases named in the same sentence as NLRP3 in open-access papers (continued):
Sharing a sentence is not in itself a finding about the gene and the disease.
infection (continued). "The NLRP3 inflammasome is composed of NLRP3, ASC, and pro-caspase-1, regulating the activation of caspase-1 and following the release of IL-1β and IL-18 from innate immune cells during infection or damage." (PMID 40872501, 2025). "Notably, inflammasome scores (based on IL1B, IL18, NLRP3, GSDMD, PYCARD) remained stable in YG CMs and IMs during infection but increased consistently in AG subsets from 4 to 6 dpi." (PMID 40794649, 2025). "They prevent excessive tissue damage during infection by exhibiting reduced function of important components like caspase-1 and IL-1β, as well as inhibited activation of the NLR family pyrin domain-containing 3 (NLRP3) inflammasome." (PMID 41009960, 2025). "In WT THP-1 macrophages, specific to infection with M. tuberculosis was a small amount of caspase-4 processing and release that was not blocked by inhibition of NLRP3 with MCC950." (PMID 40272180, 2025). "We found here that in a macrophage infection model with the RIPK1-activating pathogen, Y. pseudotuberculosis, the cell death is RIPK1 driven, yet TBK1/IKKε inhibition also sensitizes cells to enhance secondary NLRP3-dependent caspase-1 activation." (PMID 40053580, 2025). "The exacerbated infection in Tercko/ko mice correlates with heightened inflammation, manifested by elevated interleukin-1β (IL-1β) levels and activation of the NLR family pyrin domain containing 3 (NLRP3) inflammasome within the lung." (PMID 39607755, 2024). "We next sought to determine how Casp1−/−, Casp11−/−, Nlrp3−/− and Asc−/− mice were protected against the infection, whereas Casp1/11−/− was not." (PMID 39533032, 2024). "We established stable NLRP3 knockdown and overexpression cell lines via lentiviral infection of HN6 and Cal27 cells and found that overexpression of NLRP3 could inhibit the EMT process of OSCC." (PMID 38697992, 2024). "The difference in the bacterial burden detected in the urinary tracts of MRSA-infected WT and Nlrp3−/− was not statistically significant at 6, 24, and 72 h post-infection (hpi)." (PMID 38392844, 2024). "Altogether, our findings suggest that HS induces NLRP3 inflammasome activation during infection, but that NLRP3, ZBP1, and the other innate immune sensors tested are not required to induce the inflammatory cell death caused by HS and infection." (PMID 38409108, 2024). "As with JAK-STAT signalling and the NF-κB transcription pathway, the NLRP3 inflammasome is a pertinent part of the innate immune system response to the SARS-CoV-2 infection, but later in the infection, it leads to the development of and sustains the hyperinflammation in the lungs." (PMID 39051370, 2024). "qPCR analyses of BALF cell lysates demonstrates that there was a notable elevation in Nlrp3 gene expression after PA infection, which was substantially reduced in DKO mice compared with WT counterparts, suggesting a regulatory effect of PADI2 and PADI4 on Nlrp3 expression." (PMID 39405117, 2024). "While we observed minimal inflammasome activation in a RAW 264.7 infection model, we cannot exclude the possibility that SARS-CoV-2 may activate the NLRP3 inflammasome in other cell types or in vivo as indicated by other studies." (PMID 38798602, 2024). "Infection of macrophages and monocytes induces pyroptosis, a type of inflammatory cell death, through the NACHT, LRR and PYD domains containing protein 3 (NLRP3) inflammasome, neutralising the virus but releasing large amounts of IL-1β and IL-18 in the process." (PMID 39051370, 2024). "This suggests NLRP3 activation has a negative impact on BALB/c mice during infections with L. major." (PMID 38623843, 2024). "As a consequence, we interrogated if mAdV3 is generally able to modify host inflammasome responses by individually activating NLRP3 (by nigericin treatment), AIM2 (by poly-dAdT transfection) and PYRIN (by treatment with UCN-01) and NLRC4 (infection with SPI-1 induced Salmonella)." (PMID 39366977, 2024).
infection (continued). "Results reveal that the activation of NLRP3 inflammasome detected during the infection of PMA-treated THP1 macrophages with SARS-CoV-2 does not require the purinergic receptor P2X7." (PMID 37920468, 2023). "Therefore, the innate response to in vitro infection of macrophages with both LAMV and WT MeV includes production of IL-6 and TNFα and activation of the NLRP3 inflammasome to release IL-1β and IL-18." (PMID 36851476, 2023). "Additionally, mRNA levels of pyroptosis-related genes (NLRP3, ASC, caspase-1, GSDMD, IL-18, and IL-1β) in the kidneys with W24Δhcp1 infection are considerably lower than in those with WT W24 infection." (PMID 36977062, 2023). "Infection by Pseudomonas aeruginosa induces mitochondrial damage and mtROS alongside the release of ox-mtDNA in a BAX-dependent manner that activates the cGAS, TLR9, and NLRP3 and NLRC4 inflammasomes." (PMID 37001140, 2023). "The IL-1β level in the bronchoalveolar lavage fluid (BALF) of Nlrp3−/− mice is lower than that in WT mice, while the levels of MIP2, CXCL1, TNFα, and IL-6 are either lower than, or the same as, in WT mice on day 3 after infection." (PMID 37376638, 2023). "To determine whether mGBP1 could modulate IAV‐induced inflammasome activation, we infected primary WT, NLRP3−/− and GBP1−/− BMDMs with IAV [multiplicity of infection (MOI) 25] for 16 h." (PMID 36744765, 2023). "Although we were able to reproduce their observations using bone marrow neutrophils that were not primed with LPS prior to infection, we reported that NLRP3 expression in neutrophils needs to be induced by TLR priming." (PMID 37730693, 2023). "In conclusion, our study results show the participation of the NLRP3 inflammasome in the secretion of IL-1β during infection with the NADL cp-BVDV strain; furthermore, we found a possible relationship between the activation of the NLRP3 inflammasome and viral replication." (PMID 37515181, 2023). "A similar case occurred during an infection of CRIB cells with BoHV-1, which tested the activations of IFI16 and NLRP3 upstream of caspase 1 and found a decrease in the viral titer of cells treated with glyburide, which inhibits the indirect action of the inflammasome." (PMID 37515181, 2023). "A previous study has shown a role for PFO, but not lecithinase, in NLRP3 activation in BMDMs following 3 h of infection with C. perfringens." (PMID 37073791, 2023). "Furthermore, components of the NLRP3 inflammasome activation pathway, including NLRP3 itself, caspase-1, caspase-1 p20, and ASC, were all elevated at the protein level 12 h post-infection." (PMID 37594276, 2023). "Results from our experiments with treatment of BMDMs with CA and ∆yopK Yptb mutant infection showed that there was a nonsignificant decrease in IL-1β release which can be attributed to the inhibition of NLRP3 but not of the NLRC4 inflammasome." (PMID 37787552, 2023). "Mechanistically, infection triggers the formation of the RIPK1-RIPK3 complex, which promotes phosphorylation of dynamin-related protein 1 (DRP1) and translocation to mitochondria, thereby driving mitochondrial damage and NLRP3 inflammasome activation." (PMID 36845112, 2023). "Next, we evaluated the role of IRF1 in mediating cell death in response to infection with E. coli and Citrobacter rodentium, which activate the noncanonical NLRP3 inflammasome through caspase-11 activation." (PMID 37557956, 2023). "In addition to its participation in infection, VIM also plays a critical role in lung inflammation and fibrosis through interaction with NLRP3 (NACHT, LRR, and PYD domains-containing protein 3)." (PMID 35078919, 2022). "During the chronic stages of infection, NLRP3- but not NLRC4- dependent cell death correlated with the expression of fliF in ST isolated from various organs." (PMID 34864057, 2022). "Likewise, when infection by HIV affects the CNS, a sustained NLRP3 inflammasome-dependent response leads to neurological damage specifically affecting microglial cells." (PMID 35783102, 2022).
infection (continued). "Furthermore, the enhancement effects of NLRP3 and COX2 were significantly higher in the PRV single-infection group and two sequential infection groups than those in the coinfection group (PCV2+PRV)." (PMID 35457287, 2022). "Caspase-1 activation was significantly increased in Nlrc4−/− BMDMs during infection with ΔfliCΔgalE and ΔfliCΔgalE::pBAD33 strains compared to ΔfliC, but no such differences were observed in Nlrp3−/− BMDMs infected with different mutant strains." (PMID 35630356, 2022). "Activation of the NLRP3 inflammasome is induced by promoting oxidized mitochondrial DNA (mtDNA) release and caspase-3/7-dependent K+ efflux in fever with thrombocytopenia syndrome (SFTS) virus (SFTSV) infection, DNA damage, chemotherapy, or cellular stress." (PMID 36818726, 2022). "In support of this, recent observations indicate that administration of NLRP3 inhibitor at the acute stage of IAV infection becomes detrimental to the host, but NLRP3 inhibitor administration at a later stage of the infection promotes better survival and recovery of the mice." (PMID 35587190, 2022). "In addition, inflammation-related genes including NLRP3, IFI16, IL6, IL1A, CXCL2, and CCL6 were upregulated, further confirming that infection by T. gondii induces a robust immune response to limit infection." (PMID 35012632, 2022). "An earlier study showed that after infection with influenza virus or encephalomyocarditis virus (EMCV), MFN2 could interact with NLRP3 to promote the recruitment of NLRP3 to mitochondria, and subsequently induce IL-1β secretion." (PMID 35250595, 2022). "The non-canonical NLRP3 inflammasome represents an additional layer of defense during infection and is mainly activated in response to intracellular pathogens." (PMID 35406754, 2022). "STEC O113 ΔsubAB infection clearly enhanced formation of the NLRP3/pro-caspase-1 assembly but SubABwt treatment did not." (PMID 35345462, 2022). "The expression levels of endogenous NLRP3 were not affected by pH240R during ASFV or ASFV-ΔH240R infection." (PMID 36326277, 2022). "Critical role for the ESX-1/EsxA in NLRP3 activation has also been reported during the infection with non-tuberculous mycobacteria species including Mmar, and Mkan." (PMID 35237260, 2022). "We found that SubAB reduced activation of the STEC O113:H21 infection-induced non-canonical NLRP3 inflammasome and interleukin (IL)-1β and IL-18 production in murine macrophages." (PMID 35345462, 2022). "Similarly, the expression of GLUT1, MCT4, NLRP3, and the mature form of IL‐1β increased in the setting of MRSA, HK‐MRSA, and VT‐MRSA infection (Fig EV1B)." (PMID 36354099, 2022). "Location analysis of NLRP3 receptor using mouse NLRP3 mAbs showed that NLRP3 displayed puncta-like surrounding nuclear after infection with A. sobria, and in contrast, no NLRP3 signals were detected in the unstimulated cells." (PMID 34513725, 2021). "At 6 and 12 h post-infection, the mRNA expression levels of caspase-3, caspase-1, GSDMD, RIPK3, MLKL, NLRP3, IL-1β, and IL-18 were upregulated in RAW264.7 macrophages infected with either E. faecalis CA1, CA2, or OG1RF strains compared to the levels in the control group." (PMID 34513732, 2021). "We next performed LDH release assays to confirm that failure of F. tularensis LVS to replicate in the Nlrp3−/− macrophages was not on account of enhanced cell death of the Nlrp3−/− macrophages following infection." (PMID 34690967, 2021). "MTB bacterial burden in lungs and spleens, IL-1β and IL-1α concentrations in lung homogenates, the size, morphology and cellular composition of the lung lesions are not affected by NLRP3 absence following infection with virulent MTB via aerosol." (PMID 33503864, 2021). "However, infection with LV-sh-HSPA8 efficiently suppressed NF-κB and NLRP3 inflammasome activation (p < 0.05)." (PMID 34362408, 2021).
infection (continued). "However, during late-stage infection, PLY stimulation leads to increased NLRP3 expression that induces alveolar epithelial cells and macrophages to over-release mature inflammatory cytokines." (PMID 35111047, 2021). "This suggests that during later stages of infection when the inflammasome has been primed by LPS, DAMPS or other viral factors, the E protein in combination with viral RNA, may promote NLRP3 inflammasome activation." (PMID 34952919, 2021). "In our study, we found that the significance of NLRP3 to H2-induced cell death was observed in the early, but not the late, infection hour." (PMID 34009097, 2021). "Relative gray values showed that the NLRP3 protein was significantly upregulated at various infection doses compared to the control group (***p < 0.001) and no protein was detected in the C group." (PMID 34869071, 2021). "Images captured by fluorescence microscopy showed that NLRP3 aggregated in the perinuclear region after infection with V. alginolyticus, whereas no signals were observed in untreated cells." (PMID 34869071, 2021). "NLRP3 and caspase-1 protein expression in the LPS + ATP group and the HPI groups increased gradually with time post-infection, which is similar to the pattern of increased caspase-1 protein content in human monocyte macrophages following Helicobacter pylori infection." (PMID 33678162, 2021). "We noted an increase, although nonsignificant, in the numbers of Golgi fragments per cell in the U937 NLRP3 KO cells compared to U937 WT cells, in the absence of infection (NI, black bars)." (PMID 33208442, 2021). "After 24h, the bacterial numbers in the Nlrp3−/− macrophages did not increase from those observed at 4h post-infection." (PMID 34690967, 2021). "Nlrp3−/− mice infected with F. tularensis LVS had significantly higher levels of IL-1β, IL-6, IL-12p40, G-CSF, GM-CSF, TNF-α, and RANTES as compared to the wild-type mice on day 3 post-infection." (PMID 34690967, 2021). "In previous studies, immunocompetent WT mice and mice lacking the inflammasome components like NLRP3 or absent in melanoma 2(AIM2) do not succumb to infection with A. fumigatus." (PMID 34222495, 2021). "IRF8 is required for the optimal activation of the NLRC4 (NLR family CARD domain containing 4) and NLRP3 (NLR family pyrin domain containing 3) inflammasome activation after infection with Gram-negative bacteria to initiate inflammatory responses." (PMID 34067819, 2021). "Wild-type and Nlrp3−/− macrophages were infected with 100 MOI (bacteria:cell ratio) of F. tularensis LVS, and intracellular bacterial numbers were quantitated at 4- and 24-h post-infection." (PMID 34690967, 2021). "Unlike the pattern observed in the liver, only splenic caspase-1, IL-1β, and GSDMD increased during S. mansoni infection; whereas levels of NLRP3 and IL-18 did not increase during infection." (PMID 34161342, 2021). "Surprisingly, neither NAIP silencing nor further inhibiting NLRP3 with MCC950 treatment affected caspase‐1 activation or pyroptosis during infection with SPtA 9150." (PMID 33355403, 2021). "In addition, activation of inflammasome and transcription of IL-1β by modified vaccinia virus Ankara (MVA) infection is dependent on the crosstalk between TLR2-MyD88 and the NLRP3." (PMID 34638790, 2021). "After infection with the RNA virus SARS-CoV-2, the body responds through the innate defense system (TLR) that is activated, and through inflammatory pathways, as a defense shield (NLRP3 and NF-κB)." (PMID 34066560, 2021). "In addition, after SFTSV infection, IL-1β release significantly decreased in NLRP3 knockout THP-1 macrophages than wild type cells, but it was higher than mock infection in NLRP3 knockout macrophages." (PMID 33708197, 2021). "Based on previously published findings, we hypothesised that Mtb induces the assembly of one of the ASC-dependent inflammasomes, NLRP3 or AIM2, upon infection of macrophages." (PMID 32385301, 2020).
infection (continued). "The role of NLRP3 inflammasomes and whether VZV can actively modulate this at other key sites of infection such as human ganglia has yet to be explored." (PMID 32038653, 2020). "We observed that the antioxidant NAC specifically inhibited H2O2-elicited NLRP3 inflammasome activation (sterile) but not that with Fn U112 infection (bacterial)." (PMID 32983094, 2020). "For example, experimental infection with L. major resulted in nonhealing cutaneous lesions being this fact related to increased IL-1β production via NLRP3 inflammasome and local neutrophil recruitment." (PMID 31961876, 2020). "Our understanding of how the NLRP3 infammasome is controlled during infection remains incomplete, particularly since there is little evidence that NLRP3 binds to microbial ligands directly." (PMID 32750090, 2020). "In contrast, infection with an HAdV lacking VA RNAI expression failed to inhibit the NLRP3 inflammasome." (PMID 33086737, 2020). "During infection by Gram‐negative bacteria, the NLRP3 inflammasome can be indirectly activated by murine caspase‐11 (represented by caspase‐4 and 5 in humans), through what is now known as the ‘non‐canonical’ inflammasome signalling pathway." (PMID 32185892, 2020). "Even though P2X7R activation appears to enhance IL-1β production through the noncanonical NLRP3 in vitro, its participation in the control of in vivo infection by L. amazonensis has not been addressed." (PMID 33061823, 2020). "Under conditions of infection with WT V. vulnificus, HT-29 cells upregulated KLF2, KLF4, and KLF6 and downregulated NLRP3, TLR4, and CXCR4, suggesting that the MARTX toxin interrupts inflammatory responses, NF-κB signaling, and mitogen-activated protein kinase (MAPK) signaling in infected cells." (PMID 32817457, 2020). "In this study, we found that the survival rate of PA+NLRC4−/− mice was significantly improved compared with PA+WT mice and PA+NLRP3−/− mice, suggesting that the activation of NLRC4 inflammasome may aggravate infection and increase mortality." (PMID 33489931, 2020). "This agrees with prior work from our group using a mouse model of S. aureus brain abscess, where infection was localized to a defined area of the brain parenchyma, which also showed no involvement for NLRP3." (PMID 32290861, 2020). "Our previous studies show that infection with either P. vivax or P. falciparum prime circulating monocytes to express an inflammasome gene signature, form AIM2, NLRP3, and NLRP12 specks, express active caspase-1, and produce high levels of IL-1β, when challenged with LPS18,19,32." (PMID 32929083, 2020). "Furthermore, we pretreated BMDMs with the Nlrp3 inhibitor (MCC950) and Caspase-1 inhibitor (Z-YVAD-FMK) prior to the infection with SS2, and we observed the expected significant inhibitions to the IL-1β release and cytotoxicity." (PMID 32922370, 2020). "The NLRP3-mediated response to influenza A virus (IAV) has been extensively studied and plays a crucial role in protecting the host while helping in clearing the infection." (PMID 33072117, 2020). "Under the infection of Salmonella, NLRC4 and NLRP3 inflammasomes could be activated within 1 h, cut the pro-caspase-1 into active caspase-1 in macrophages and induce pyroptosis." (PMID 33324360, 2020). "We reasoned the relative reduction in pyroptosis, and the increase in necrosis 24–48 h of infection could be due to prolonged stimulation of Toll-like receptor (TLR) signalling, which has been reported to inhibit NLRP3 inflammasome activation." (PMID 32385301, 2020). "In vivo, IL-18 releases in serum and parasite burdens in peritoneal exudate cells were significantly increased in PG-treated WT mice after infection with N. caninum; however, IL-18 productions and parasite burdens were not changed in PG-treated Nlrp3−/− mice." (PMID 32891167, 2020).